SMAD3 (SMAD family member 3)
Diseases named in the same sentence as SMAD3 in open-access papers (continued):
Sharing a sentence is not in itself a finding about the gene and the disease.
renal fibrosis (continued). "To elucidate the underlying mechanism by which HDAC11 induces EMT and renal fibrosis in the UUO model, we investigated the effect of HDAC11 inhibition on the phosphorylation of Smad3 (p-Smad3) and STAT3 (p-STAT3) in the kidney and cultured RTPCs." (PMID 40386380, 2025). "In a mouse model of unilateral ureteral obstruction, IL-10 inhibits inflammatory factor expression and ameliorates renal fibrosis by antagonizing the TGF-β/Smad3 and NF-κB signaling pathways." (PMID 40092979, 2025). "Our prior studies have demonstrated that GAS5 inhibits renal fibrosis via microRNA-mediated pathways, including suppression of miR-21 activity and regulation of the Smad3/miRNA-142-5p axis in TGF-β signaling." (PMID 40685500, 2025). "The most significant finding in this study is the discovery of a new mechanism by which Smad3 mediates renal fibrosis via GPX4-dependent ferroptosis." (PMID 41079940, 2025). "We then investigated the regulatory mechanism of Smad3 in GPX4-dependent ferroptosis during renal fibrosis in a mouse model of UUO induced in Smad3 KO/WT mice." (PMID 41079940, 2025). "The TGF-β/Smad pathway has long been recognized as the ‘master regulator’ driving renal fibrosis, making it a prime target for drug development, exemplified by the Smad3 inhibitor Specific Inhibitor of Smad3 (SIS3)." (PMID 41333019, 2025). "Ferroptosis-derived lipid peroxides and DAMPs can activate the TGF-β/Smad3 pathway, creating a feed-forward loop that exacerbates renal fibrosis." (PMID 41487503, 2025). "An enhancement in Smad3 signaling and renal fibrosis were observed in mice with Smad2 conditional knockouts." (PMID 40141345, 2025). "All these findings demonstrated that GPX4 is a downstream target gene of Smad3 and is protective in Smad3-mediated renal fibrosis." (PMID 41079940, 2025). "We first reveal that METTL3 facilitates M2‐driven MMT by modulating the TGF‐β1/Smad3 pathway, contributing to renal fibrosis in CAR." (PMID 39869489, 2025). "The progression of DN is closely associated with dysregulated inflammation and immune responses, where the TGF-β/Smad3 signaling pathway serves as a central driver of renal fibrosis." (PMID 41487503, 2025). "Studies indicate that lncRNAs Erbb4-IR and LRN9884 participate in renal fibrosis and inflammation during DN progression by influencing Smad3 activity." (PMID 41487503, 2025). "Our recent studies also demonstrated that blocking class IIa HDACs with MC1568 increased Smad7 expression and decreased Smad3 expression in a murine model of UUO-induced renal fibrosis." (PMID 41275091, 2025). "The level of acetylation of Smad3 (Ac-Smad3) was elevated in rats with cardiac fibrosis, and renal fibrosis but it was reduced in the normal myocardium and nephridial tissue of rats." (PMID 40191425, 2025). "A study showed that EGCG improved renal fibrosis by inhibiting transforming growth factor‐beta 1 (TGF‐β)/mothers against decapentaplegic homolog 3 (Smad3) pathway in diabetic mice." (PMID 41019174, 2025). "Studies have shown that SMAD2 and SMAD3 are widely activated in renal fibrosis of CKD patients and animal models." (PMID 40514734, 2025). "Building upon prior evidence that FN mitigates renal fibrosis through SMAD3/ATF3/SLC7A11 pathway inhibition, we extended these observations to hepatic fibrosis using comprehensive analyses." (PMID 40852727, 2025). "As a downstream target gene of Smad3, GPX4 is negatively regulated by TGF-β via a Smad3-dependent mechanism but exerts a protective role in Smad3-mediated renal fibrosis." (PMID 41079940, 2025). "Hyperglycemia drives renal injury through activation of the RAAS and accumulation of advanced glycation end products (AGEs), while aberrant activation of key signaling pathways such as TGF-β/Smad3 and NF-κB further promotes renal fibrosis." (PMID 41487503, 2025). "All these in vivo and in vitro findings reveal a protective role for GPX4 in Smad3-mediated renal fibrosis." (PMID 41079940, 2025).
renal fibrosis (continued). "By blocking the Notch pathway’s activation, TGF-β production, and Smad2 and Smad3 phosphorylation, Notch inhibitors can markedly lessen the severity of renal fibrosis." (PMID 40822939, 2025). "(−)-Epigallocatechin gallate is one of the main bioactive components of green tea and has been shown to reduce renal fibrosis by targeting Notch via the inhibition of the TGFβ/SMAD3 pathway." (PMID 41020857, 2025). "The TGFβ/Smad3 axis has been shown to promote renal fibrosis, whereas Smad2 is considered to counteract the profibrotic activity of Smad3." (PMID 40076647, 2025). "Mechanistically, deletion of DUSP1 promotes the nuclear translocation of Smad3, a crucial mediator of renal fibrosis, primarily through dephosphorylation at its 423/425 residue." (PMID 40213676, 2025). "Reports indicate that TGF-β1 upregulates the miR-21 level via a SMAD3-dependent mechanism during the course of renal fibrosis." (PMID 40486272, 2025). "NETs were found to promote the conversion of macrophages to myofibroblast-like phenotypes via the TGF-β1/Smad3 signaling pathway in a renal fibrosis model." (PMID 40109341, 2025). "The TGF-β/Smad3 signaling pathway is one of the classic signaling pathways for the treatment of renal fibrosis." (PMID 39687299, 2024). "Previous studies have reported that Sirt1 can inhibit renal fibrosis induced by TGF-β1 signal transduction by deacetylating Smad3 and Smad4." (PMID 38446387, 2024). "Dysregulation of TGF-β-driven signaling is the main cause of EMT and renal fibrosis, and in particular, blocking the TGF-β/Smad3 pathway substantially attenuates fibrosis in animal models of kidney disease." (PMID 39661589, 2024). "Tempol treatment inhibited NF-κB-mediated inflammation and TGF-β1/Smad3-induced renal fibrosis signaling pathway activation." (PMID 38395806, 2024). "A study reported that a novel long non-coding RNA (lncRNA) called Erbb4-IR is accountable for renal fibrosis that is mediated by TGF-β/Smad3, making it a selective therapeutic target for CKD." (PMID 39234105, 2024). "While studying the possible underlying mechanisms for this, it was found that CKD-bearing mice given Tempol (a Superoxide Dismutase-Mimetic) exhibited reduced renal fibrosis along with decreased signaling via TGF-ß/Smad3, EGFR and MAPK pathways." (PMID 39234105, 2024). "Our findings suggest that aerobic exercise can inhibit the TGF-β1/Smad3 signaling pathway by modulating Klotho expression, thereby mitigate age-related renal fibrosis." (PMID 39325739, 2024). "Abnormal expression of TGF-β1 can induce renal fibrosis through the classical Smad pathway, in which Smad3 increases fibrin transcription and promotes tissue fibrosis, while Smad7 inhibits tissue fibrosis." (PMID 39371929, 2024). "Supporting this, it was also found that by suppressing miR-29b, renal fibrosis was enhanced in T2DN by Erbb4-IR through a Smad3-dependent lncRNA." (PMID 39234105, 2024). "Class IIa HDAC inhibitor MC1568 inhibits EMT-mediated renal fibrosis by inhibiting the activation of TGF-β/SMAD3 and the NF-κb signaling pathway, and upregulating the expression of BMP-7, KLOTHO protein." (PMID 38929505, 2024). "As the key driver of renal fibrosis, its down-stream Smad2 and Smad3 are activated in the fibrotic kidney of CKD patients and animal models." (PMID 38603722, 2024). "We next investigated the molecular mechanisms through which blockade of Smad3 inhibits renal fibrosis in T2DN in both prediabetic and diabetic-treated db/db mice." (PMID 38164169, 2024).
renal fibrosis (continued). "The expression of Smads is regulated by TGF-β1, with Smad2 and Smad3 being most closely related to renal fibrosis." (PMID 39712489, 2024). "The findings revealed heightened expression of miR-10a and miR-10b in the kidneys of UUO mice, accompanied by a substantial increase in p-Smad3 and renal fibrosis-related proteins." (PMID 38791272, 2024). "Further in vitro tests indicated that these miRNA combinations enhanced pre-fibrotic molecules via the SP1 and Smad3/TGFβ pathways, promoting renal fibrosis." (PMID 39104393, 2024). "It has been demonstrated that Smad3 mainly mediated renal fibrosis, and deletion of Smad3 reduced fibrogenesis." (PMID 38357745, 2024). "This inhibition consequently mitigates the activation of the TGF-β1/Smad3 and Wnt/β-catenin signaling pathways, establishing a delayed and benign feedback loop in renal fibrosis." (PMID 39325739, 2024). "CD74 regulates the transcription of fibrotic genes, including Col I, fibronectin and α-SMA through binding to their promoters, and the activation of TGF-β-Smad3 signaling to increase renal fibrosis in ADPKD kidneys." (PMID 38534333, 2024). "It upregulated the expression of Sirt1 and inhibited the TGF-β/Smad3 pathway, thus significantly and markedly improving renal fibrosis and renal function." (PMID 39687299, 2024). "Both miR-10a/b can negatively regulate the target gene VASH-1, thereby promoting the phosphorylation of Smad3 and driving the development of renal fibrosis." (PMID 38791272, 2024). "OA inhibits the TGF-β/Smad3 signaling pathway through different targets and has great potential for the treatment of renal fibrosis." (PMID 39687299, 2024). "In CKD rat models, DFX inhibits the TGFβ-Smad3 pathway, reducing inflammation and oxidative stress while attenuating renal fibrosis." (PMID 39857243, 2024). "Previous reports have suggested that the TGF-β1/Smad2/Smad3 signaling pathway is involved in EMT-mediated renal fibrosis." (PMID 39451219, 2024). "In the UUO model, PRMT1 contributes to renal fibrosis by modulating the TGF-β/SMAD3 pathway, a process attenuated by the inhibitory effects of AMI-1." (PMID 38929505, 2024). "Specifically, it ameliorates renal fibrosis in DN by suppressing Smad3/NOX4/SLC7A11-mediated ferroptosis in tubular cells." (PMID 39769044, 2024). "The activation of the TGF-β1/Smad3 signaling pathway is crucial to the development of renal fibrosis." (PMID 38576481, 2024). "It was observed that the expression levels of TGF-β1 and Smad3 in group AE were significantly lower compared to levels in group A (P<0.05), which indicated that aerobic exercise significantly improved renal fibrosis." (PMID 39325739, 2024). "For example, miR-192 mediates TGF-beta/Smad3-driven renal fibrosis in a mouse model of UUO and a rat remnant kidney model." (PMID 39138396, 2024). "A potential mechanism by which SMAD3 contributes to renal fibrosis is the promotion of cell cycle arrest." (PMID 38982119, 2024). "Studies have shown that activation of FXR can inhibit the activation of TGF-β1 pathway by down-regulating the expression of Smad3 and up-regulating the expression of Smad7, thereby alleviating renal fibrosis." (PMID 39371929, 2024). "Given the important role of TGF-β/Smad3 signaling in renal fibrosis, the expression of Smad3 was examined." (PMID 39687299, 2024). "In this study, we show a novel mechanism of the regulation of TGF-β transcription by MIF-CD74 in renal epithelial cells and fibroblasts, which should contribute to the activation of Smad3 signaling to promote renal fibrosis in ADPKD kidneys." (PMID 38534333, 2024). "P2Y12 is highly expressed by macrophages in fibrotic kidneys and promotes MMT-mediated renal fibrosis through TGF - β/Smad3 signalling." (PMID 39445007, 2024). "It has been shown to mitigate renal fibrosis induced by UUO through the inhibition of Smad3-mediated ferroptosis." (PMID 39769044, 2024).
renal fibrosis (continued). "Previous research has demonstrated that nicotinamide supplementation can reduce renal fibrosis by activating the TGF-β/Smad3 signaling pathway." (PMID 37953778, 2023). "A previous study demonstrated that GAS5 attenuated renal fibrosis by modulating the Smad3/miRNA-142-5p axis." (PMID 36918759, 2023). "To investigate the possible cause of HDAC3 upregulation, we focused on the TGF-β1 signaling pathway since TGF-β1/SMAD3 signaling has previously been reported to directly promote HDAC3 transcription in renal fibrosis." (PMID 37951958, 2023). "SMAD4 plays a key role in regulating TGF-β–induced collagen expression and promotes SMAD3-mediated renal fibrosis while activation of EGFR serves as prognostic biomarker during chronic kidney disease." (PMID 37707956, 2023). "In the AKI-CKD mouse model, serum FGF-23 levels were increased, and renal fibrosis occurred; moreover, the protein expression of β-catenin and p-Smad3 was upregulated." (PMID 37016338, 2023). "TXNIP deletion attenuates renal fibrosis and damage by regulating SMAD3 and p38/ERK MAPK phosphorylation in a unilateral ureteral obstruction (UUO) mouse model of renal interstitial fibrosis." (PMID 37394581, 2023). "In fact, it has been reported that knockout of Smad3 can effectively prevent renal fibrosis in the mouse UUO injury model." (PMID 36479618, 2023). "Smad2 and Smad3 are almost similar (90%) but exhibit opposite effects, i.e., Smad2 is renal protective, whereas Smad3 is actively involved in renal fibrosis." (PMID 37559381, 2023). "This compound protects the kidney from injury by blocking TGF-β/Smad3-mediated renal fibrosis and NF-κB-induced renal inflammation." (PMID 36836916, 2023). "Highly expressed EVL binding to Smad7 abrogated the Smad7‐induced suppression of transforming growth factor‐β (TGF‐β1)/Smad3 signal transduction, which conversely facilitated renal fibrosis progression." (PMID 37537731, 2023). "By using the RNA sequencing technique, we have previously identified a series of Smad3-dependent long ncRNAs (lncRNAs) related to renal fibrosis and inflammation in rodent models." (PMID 37449045, 2023). "The levels of total protein extract of kidney tissue also confirmed renal fibrosis activation with the increment of these fibrotic markers and phosphorylated SMAD family member 3 (p‐SMAD3)." (PMID 37452432, 2023). "Smad3 has been demonstrated to mediate renal fibrosis via both the downregulation of miR-29 and miR-200 and the upregulation of miR-21 and miR-192." (PMID 37760798, 2023). "Of them, the lncRNA Erbb4-IR is a novel Smad3-dependent lncRNA that mediates renal fibrosis in obstructive and diabetic nephropathy." (PMID 37449045, 2023). "In the present study, it has been shown that CTRP13 can ameliorate UUO-induced kidney dysfunction via NF-κB-driven kidney inflammation and TGF-β1/Smad3-mediated renal fibrosis." (PMID 38255158, 2023). "The activation of SIRT1 has been shown to inhibit TGF-β/Smad3 signaling, thereby reducing Smad3 acetylation and improving renal fibrosis in 5/6 nephrectomized rats." (PMID 38074159, 2023). "miR-433 activates the transforming growth factor-β (TGF-β)/Smad3-Azin1 signaling pathway, thus promoting renal fibrosis." (PMID 37760798, 2023). "Through some experiments with the SMAD3 knockout gene, a lower renal fibrosis level in diabetic, obstructive and hypertensive nephropathy were evidenced." (PMID 37762322, 2023). "In UUO mice, FXR agonist protected against renal fibrosis and downregulated Smad3 expression, which is a critical signaling protein in renal fibrosis." (PMID 36768731, 2023). "Pro-fibrotic role of Smad3 in renal fibrosis was further confirmed by the study where Smad3 deletion suppressed the fibrosis in a rodent model of fibrogenesis." (PMID 37559381, 2023). "In diabetic Sprague–Dawley rats, genistein improves renal fibrosis by regulating the TGF-1/Smad3 pathway and reduces oxidative stress by activating the Nrf2-HO-1/NQO1 pathway." (PMID 36836916, 2023).
renal fibrosis (continued). "TGF-β1, a mediator of renal fibrosis, activates Smad3, which in turn regulates target genes for renal fibrosis." (PMID 37408253, 2023). "The protein expression levels of α-SMA, ED-1, TGF-β1, p-Smad2, and p-Smad3 were detected by western blot to analyze renal fibrosis and its regulatory mechanism." (PMID 36648018, 2023). "PRMT1 can promote renal fibrosis injured by left ureteral obstruction through the TGF‐β1/Smad3 signaling pathway, suggesting a key role of PRMT1 in TGF‐β1/Smad3 signaling." (PMID 37525933, 2023). "Resveratrol has been reported to ameliorate renal fibrosis by enhancing the binding between Sirt1 and Smad3, reducing acetylation levels of Smad3." (PMID 37866886, 2023). "Overall, these data suggested that SMAD2 and SMAD3 are important targets of SIRT2 against renal fibrosis." (PMID 37777567, 2023). "Ang II and AGEs are also able to induce renal fibrosis by activating Smad3 signaling via TGF-β-dependent and-independent pathways." (PMID 35541902, 2022). "TGF-β is one of the most important factors leading to the development of renal fibrosis, and Smad3 is an important downstream molecule of TGF-β signaling pathway." (PMID 35439976, 2022). "TGF-β1/Smad3 signaling is a common pathway involving in renal fibrosis, which contributes to extracellular matrix (ECM) deposition, tubular epithelial–mesenchymal transition (EMT) and kidney inflammation." (PMID 36536448, 2022). "Many studies have documented that TGF-β1 stimulates renal fibrosis primarily through activation of the Smad3 pathway." (PMID 35847036, 2022). "TGF-β signaling promotes renal fibrosis in CKD primarily through the downstream transcriptional factor Smad3." (PMID 36091385, 2022). "In CKD rats, DFX treatment can mitigate renal fibrosis by the inhibition of TGF-β1/Smad3, inflammation, and oxidative stress pathways." (PMID 35050181, 2022). "Hif-1α has also been reported to have crosstalk with several pathways that promote fibrosis, such as Notch, PI3K/Akt, and Smad3 pathways during the process of renal fibrosis." (PMID 36675720, 2022). "Dioscin, a natural product in Rhizoma Dioscoreae, has been found to up-regulate the expression of the SIRT3 gene, inhibit renal fibrosis mediated by TGF-β1/Smad3 signaling pathway, and ameliorate fructose-induced kidney injury." (PMID 35978370, 2022). "Conclusively, findings in this study demonstrate that let-7i-5p is a pro-fibrotic microRNA and is regulated by the TGF-β/Smad3 pathway in renal fibrosis." (PMID 36091385, 2022). "P144 decreases renal fibrosis by blocking TGF-β1/SMAD3 signals and modulating the polarization of macrophages, suggesting its possible therapeutic potential in ischemia–reperfusion injury-induced renal fibrosis." (PMID 36534225, 2022). "GQ5 (a small compound isolated from Resina Toxicodendron) can block the interaction of Smad3 with TβRI and attenuates renal fibrosis." (PMID 35541902, 2022). "Meanwhile, we elucidated a novel cross-regulation between MyD88 and STAT3 or Smad3, thus reaffirming the plausibility of MyD88 as a potential therapeutic target for renal fibrosis." (PMID 35628363, 2022). "CRP can activate Smad3 to mediate renal fibrosis directly via the CD32b-ERK/p38 MAP kinase-crosstalk pathway and indirectly through the TGF-β1-dependent mechanism." (PMID 35541902, 2022). "The TGF-β1/Smad3 signaling pathway mediates renal fibrosis and inflammation in addition to promoting the development of DKD." (PMID 36012674, 2022). "Smad3 exhibits a marked collagen deposition and contributes to the progression of renal fibrosis in db/db mice, and Smad3 knockout inhibits this process." (PMID 35966088, 2022). "BMSCs can also suppress renal fibrosis in rats with diabetic nephropathy by inhibiting the TGF-β1/Smad3 pathway." (PMID 35672285, 2022). "It has been reported that Sirt1 can bind to Smad3 to reduce the acetylation levels of Smad3 and inhibits renal fibrosis." (PMID 35541902, 2022).